APC (APC regulator of Wnt signaling pathway)
Diseases named in the same sentence as APC in open-access papers (continued):
Sharing a sentence is not in itself a finding about the gene and the disease.
adenocarcinoma (112 papers, 2003 to 2025). A common cancer characterized by the presence of malignant glandular cells. "APC was the most significantly mutated gene in both canine adenomas and adenocarcinomas (Frequent Alteration of the Tumor Suppressor Gene APC in Sporadic Canine Colorectal Tumors)." (PMID 38098990, 2023). "Case 2 was a woman in her 30 s who had a mutation of APC exon 1B, and preoperative biopsy revealed suspected adenocarcinoma." (PMID 35435526, 2022). "As expected, among the APC variant carriers with available medical history, half of the JRTs had current and/or previous history of adenocarcinomas of the stomach or large intestine." (PMID 35717217, 2022). "Recent efforts to model metastatic disease with compounding mutations in the intestine of APC-deficient mice yielded tumors that readily progressed to adenocarcinoma but showed limited metastasis." (PMID 31526760, 2019). "As to the contribution of Ad2Sc, both subgroup analysis and TCGA analysis showed significantly greater OR in the high Ad2Sc than that in the low Ad2Sc group, which suggested the APC methylation test has better diagnostic performance for adenocarcinoma." (PMID 24661338, 2014). "APC mutation was common in GC, particularly in well‐differentiated adenocarcinoma." (PMID 35486034, 2022). "CRC is a heterogeneous disease at genetic level, due to the many different mutations occurring in the epithelium of the large intestine, and an early event in the adenoma to adenocarcinoma transformation is the mutation in the tumor suppressor gene Adenomatous Polyposis Coli (APC)." (PMID 35625868, 2022). "The R302X and E1306X mutations of APC were detected in several other adenocarcinomas." (PMID 23301059, 2013). "However, loss of Pten in the context of APC deficiency can lead to the development of adenocarcinoma." (PMID 21203412, 2010). "All the results above indicate that the APC methylation test would have better performance in adenocarcinoma than that in Sc, and therefore, the variation in the proportions of Ad and Sc in the samples might affect the association between APC methylation and NSCLC." (PMID 24661338, 2014). "Some adenocarcinomas develop following the mutational activation of β-catenin (CTNNB1), regulated by APC, or through an alternative pathway involving the inactivation of tumor suppressor genes responsible for DNA repair." (PMID 40310348, 2025). "Their results showed two hypomethylated genes (CDKN2A and MGMT) and three hypermethylated genes (CDH13, RUNX3, APC) in adenocarcinomas compared with SCC, with the higher sensitivity and specificity values of CDH13 and APC." (PMID 32604993, 2020). "KRAS is commonly mutated in sporadic CRCs (35–45%) and is associated with poor prognosis; according to the adenocarcinoma sequence, KRAS mutations occur after APC mutations." (PMID 33374459, 2020). "This is the reason for why FAP mutations, by abolishing APC function, lead to constitutively active WNT signaling and, in turn, to uncontrolled proliferation of colon cells, formation of polyps and adenocarcinomas." (PMID 29156563, 2017). "This autosomal-dominant syndrome is caused by germline mutations in the gene coding for the protein APC and leads to hyperactivation of the WNT/β-catenin signaling pathway, uncontrolled intestinal cell proliferation and formation of adenocarcinomas." (PMID 29156563, 2017). "Mutant KRAS therefore seems to enhance the transition from a benign adenoma to a malignant adenocarcinoma in a context of inactivation of the tumor suppressor gene adenomatous polyposis coli (APC)." (PMID 27636997, 2016).
adenocarcinoma (continued). "Adenomatous polyposis coli (APC) is methylated more frequently in human adenocarcinoma than in human ESCC." (PMID 27110300, 2016). "For example, though the biallelic loss of APC was present in almost all cases of familial APC and most CRC patients, nuclear β-catenin was rarely found in those polyps and in less than 50% of the adenocarcinoma cases." (PMID 27661103, 2016). "The elevated expression of miR-135a/b, negative regulator of APC, has been observed in adenocarcinomas as well as premalignant colorectal adenomas and correlated with concomitant reduced levels of APC leading to WNT pathway activation." (PMID 26623728, 2016). "In conclusion, this integrated analysis of the pooled data provides strong evidence that the methylation status of the APC promoter is strongly associated with NSCLC, especially for adenocarcinoma." (PMID 24661338, 2014). "The methylation status of APC promoter was strongly associated with NSCLC, especially adenocarcinoma." (PMID 24661338, 2014). "Of interest, CDON−/−APC+/1638N mice showed over 3.4-fold more of aggressive adenocarcinomas with muscularis or serosal invasion compared to CDON+/+APC+/1638N controls (p<0.01)." (PMID 23940460, 2013). "In mouse models, the loss of PTEN in the context of APC deficiency accelerates tumourigenesis through increased activation of AKT, leading to the rapid development of adenocarcinoma." (PMID 19935793, 2010). "Meltzer's group has demonstrated the significance of APC as a molecular marker for both serum and tissues of patients with adenocarcinoma of esophagus." (PMID 19149902, 2009). "More lately, it is reported that adenocarcinomas are formed in a prostate-specific APC deletion mouse model." (PMID 18478098, 2008). "Our results further support the key role of APC in duodenal adenomas/adenocarcinomas." (PMID 34584977, 2021). "Thus, mutant KRAS expression in the context of the APC-mutant colonic epithelium is sufficient to induce dysplastic adenocarcinomas." (PMID 29652830, 2018). "There is evidence that tumors with MSI develop from flat lesions via mutation in RNF43 (serrated adenoma pathway) rather than the adenoma to adenocarcinoma pathway, which is associated with gatekeeper mutations in the APC gene." (PMID 30001362, 2018). "In this syndrome, a mutation in the protein APC, leads to hyperactivation of the WNT/β-catenin signaling pathway and, in turn, to uncontrolled intestinal cell proliferation and a high risk for the formation of adenocarcinomas." (PMID 29156563, 2017).
adenocarcinoma (continued). "The group with the high proportion of adenocarcinoma had a significantly bigger OR than that of the low subgroup (P = 0.0077) which suggested that APC methylation might have subtype specificity in NSCLC." (PMID 24661338, 2014). "The incidence of adenocarcinomas was increased by more than 2.3-fold in CDON−/− APC+/1638N mice." (PMID 23940460, 2013). "Their study showed 92% hypermethylation of APC in adenocarcinoma." (PMID 19149902, 2009). "Prostate-specific deletion of APC gene in mice results in formation of adenocarcinoma." (PMID 18478098, 2008). "Likewise, APC and K-RAS, genes frequently mutated in adenocarcinomas, are rarely mutated in PJS." (PMID 25190708, 2014). "Moreover, the administration of 0.2% or 0.5% curcumin in the diet, approximately equal to 300 and 750 mg/kg curcumin per day respectively, commencing one week postweaning in APC-/+ mice, also reduced the incidence of adenocarcinoma formation as compared to untreated APC-/+ mice." (PMID 21859497, 2011). "However, silver staining of the gel for the immunoprecipitates after transfer revealed a band with a molecular weight of approximately 300 kDa in the adenocarcinoma, suggesting APC as an interacting partner with β-catenin in this tumour, in addition to Lef-1 (data not shown)." (PMID 14520463, 2003). "Previous studies have shown that abnormal methylation patterns of genes (APC, CdH1, CDKN2A, and ESR1) are not only limited to adenocarcinoma tissues but also found in precancerous BE tissues." (PMID 34222478, 2021). "Alterations in ‘typical’ adenocarcinoma key-driver genes—including APC, KRAS, NRAS, PIK3CA, PTEN, or SMAD4 —have not been detected so far." (PMID 35205133, 2022). "We did not detect mutations of the BRAF, APC, or SMAD4 genes in the adenocarcinomas, although these genes have been reported as frequently mutated in previous studies." (PMID 34422662, 2021). "In 10% of the adenocarcinoma sample, APC immunoreactivity was completely absent despite the abundant expression of the protein in the adjacent normal mucosa." (PMID 28576136, 2017). "In adenocarcinomas, as well as premalignant colorectal adenomas, oncomiRs miR-135a and miR-135b are overexpressed and directly target the 3′UTR of the APC mRNA, suppress the APC expression, and activate Wnt signaling." (PMID 28573140, 2017). "Moreover, whereas adenocarcinomas were detected in 46.4% of the CDON+/+APC+/1638N control mice, consistent with previous reports, the frequency of CDON−/−APC+/1638N mice with adenocarcinomas was markedly increased to 77.6% (p<0.05)." (PMID 23940460, 2013). "APC, KRAS, and CDKN2A were focused on in the present study, and cases with adenocarcinomas were classified based on the presence or absence of each alteration." (PMID 38672586, 2024). "With the anti-APC NH2-terminus antibody, low or absent levels of full-length APC protein were noted in adenocarcinomas and OVCAR-3 cells even though staining of tumour cells was positive." (PMID 14520463, 2003).
colorectal (33 papers, 2010 to 2025). "APC is the most frequently mutated gene in colorectal carcinogenesis, acting as a gatekeeper of the Wnt pathway by regulating β-catenin degradation." (PMID 40842629, 2025). "For colorectal carcinogenesis, it is thought that APC mutations initiate carcinogenesis by compromising apoptosis in colonic endothelial cells resulting in the creation of adenomatous polypes." (PMID 22069497, 2011). "As this occurs as the entry mutation in the process of colorectal carcinogenesis APC is here known as the gatekeeper." (PMID 20696052, 2010). "APC is mutated in the early stages of traditional colorectal carcinogenesis." (PMID 33753878, 2021). "As a tumor suppressor gene, APC is highly mutated in CRC (about 70%), and its mutation is important in colorectal tumorigenesis." (PMID 36925638, 2023). "High-throughputcellular nuclei sorting was applied to investigate the nuclear accumulationof β-catenin in APC-mutant colorectal cancercells." (PMID 36589880, 2022). "Although miR-494 has been reported as being an upregulated miRNA, the interplay between miR-494 and APC-mediated colorectal tumorigenesis progression remains unclear." (PMID 29304823, 2018). "MiR-145 mimic inhibited p72 expression, while neither miR-143 mimic nor siRNA for ERK5 seemed to have significant effect, which data demonstrate that the downregulation of p72 in the small intestine tumors of Tg/APC may be mainly elicited by miR-145." (PMID 22876303, 2012). "Because dysregulation of the Wnt/β‐catenin signaling pathway by APC inactivation is the first step in a multistep genetic model for most CRCs,42 VSNL1 may be involved in the initiation of colorectal carcinogenesis." (PMID 37096864, 2023). "Some have proposed, in contrast to colorectal carcinogenesis, that APC would not play such an essential role in SBA." (PMID 29522538, 2018). "Moreover,targeting USP7 with small molecule inhibitors (XL177A and P5091) selectivelyinhibited the growth of mutant APC-colorectal cancercells which are characterized by enhanced nuclear β-cateninaccumulation but not wildtype APC epithelial colorectalcells." (PMID 36589880, 2022).
colon polyps (27 papers, 2001 to 2025). "Whereas the number of colonic polyps has been linked to the APC gene mutation, possible genotype-phenotype correlations largely remain to be defined for the extracolonic manifestations." (PMID 19036155, 2008). "Furthermore, screenings for colonic polyps and congenital hypertrophy of the retinal pigment epithelium must be performed to exclude germline APC mutations and association with FAP." (PMID 38835742, 2024). "To further address the possible means by which RAP acts to inhibit Apc mutation-dependent colon polyp formation and progression, we studied immortalized human colon epithelial cells (HCECs) where APC expression was markedly inhibited via shRNA-mediated approaches." (PMID 24763434, 2014). "Constitutive activation of Wnt/β-catenin signaling due to mutations in adenomatous polyposis coli (encoded by APC) sensitizes colonic polyps to TRAIL activation in a murine model through downregulation of cFLIP, a potent inhibitor of the extrinsic apoptotic pathway." (PMID 23869245, 2013). "APCMin (multiple intestinal neoplasia) mice, in which the APC gene carries a truncation mutation at codon 850 and the WNT pathway is dysregulated, can develop hundreds of small intestine and colonic polyps." (PMID 26650241, 2015). "EP2 was induced in colon polyps in mice with a targeted deletion of the adenomatosis polyposis coli (APC) gene and this receptor has also a key role in the ovulatory process." (PMID 17107625, 2006). "Activation of PPARγ increases colonic polyps in the APC+/min mouse model of colon carcinogenesis." (PMID 23516550, 2013). "Interestingly, based on a review of the clinical data from the donors, we found antecedents of colon polyps in the donor in whom the APC variant was found, although we did not detect the typical APC mutations seen in FAP (Fodde R, 2002)." (PMID 36324892, 2022). "This is the first study analyzing the gene expression of APC, Wnt3A, Wnt5A, BCL9, and LEF1 in the colon polyps vs. adjacent mucosa and vs. normal mucosa from control individuals." (PMID 39200196, 2024). "In sum, our observations suggest that while not all APC mutant peptides are immunogenic, a library of empirically confirmed ones could qualify as vaccine candidates designed to target second hit somatic mutations in the APC gene that drive the formation of colon polyps." (PMID 30256815, 2018).